NANOG (Nanog homeobox)
Diseases named in the same sentence as NANOG in open-access papers (continued):
Sharing a sentence is not in itself a finding about the gene and the disease.
mesothelioma (continued). "Thus, our observation that NANOG is present in the nucleus of mesothelioma, further corroborates that differentiation processes are inhibited in mesothelioma, rendering mesothelioma a highly undifferentiated cancer." (PMID 32664372, 2020). "Immunocytochemical analysis showed that human mesothelioma line exhibited similar pattern of OCT4, NANOG and SOX2 protein expression, and that subcellular localization of NANOG and SOX2 corresponded to human mesothelioma samples." (PMID 32664372, 2020). "The mesothelioma samples used for testing OCT4, NANOG and SOX2 expression were also used for investigating the expression of phosphorylated (activated) PI3K (Tyr607; p-PI3K), phosphorylated/activated AKT (Ser473; p-AKT) and BCL2." (PMID 32664372, 2020). "The subcellular localization analysis of pluripotency factor protein expression showed that NANOG and SOX2 were expressed in the nucleus and cytosol of human mesothelioma and Mero-14 cells." (PMID 32664372, 2020). "Human mesothelium and mesothelioma expressed SOX2, NANOG, PI3K and AKT genes and proteins and POU5F1 gene, whereby NANOG, SOX2 and phosphorylated (activated) AKT were upregulated in mesothelioma." (PMID 32664372, 2020). "Similar to their proteins, NANOG and SOX2 genes were expressed in both mesothelium and mesothelioma." (PMID 32664372, 2020). "We tested the expression of OCT4/POU5F1, NANOG, SOX2, PI3K-AKT pathway and BCL2 genes and proteins in 65 samples of human mesothelioma and 19 samples of normal mesothelium." (PMID 32664372, 2020). "Samples of human normal mesothelium and mesothelioma were analyzed pathohistologically and immunohistochemically to determine the expression of the pluripotency factors, OCT4, NANOG and SOX2." (PMID 32664372, 2020). "Although NANOG and SOX2 genes were downregulated in mesothelioma compared to mesothelium, their proteins were upregulated in the cancer." (PMID 32664372, 2020). "This is the first study that extensively tested the expression of OCT4/POU5F1, NANOG and SOX2 genes and proteins in human mesothelium and mesothelioma." (PMID 32664372, 2020). "Unlike protein expression, the genes of pluripotency factors, POU5F1, NANOG and SOX2, were less expressed in mesothelioma than in mesothelium." (PMID 32664372, 2020). "Comparison of Im index showed a greater expression of NANOG and SOX2 proteins in mesothelioma than in mesothelium, indicting a dedifferentiation of mesothelioma compared to mesothelial cells from which mesothelioma originates." (PMID 32664372, 2020). "Mesothelioma cell line recapitulated the expression pattern of OCT4, NANOG and SOX2 proteins in human mesothelioma." (PMID 32664372, 2020). "We showed for the first time in human mesothelioma that PI3K and AKT genes were in positive correlation with the expression of POU5F1, NANOG and SOX2, suggesting positive regulation at the level of gene expression." (PMID 32664372, 2020). "Others have shown that H2O2 can upregulate POU5F1, NANOG and SOX2 in mesothelioma line." (PMID 32664372, 2020). "This suggests that NANOG and SOX2 are expressed almost in all cell subpopulations of mesothelioma." (PMID 32664372, 2020). "Moreover, by utilizing advantages of immunocytochemical approach, we demonstrated that SOX2 and especially NANOG are expressed in majority of Mero-14 and mesothelioma cells, not just these putative cancer stem cells." (PMID 32664372, 2020). "Since we showed that wortmannin did not significantly affect the expression of NANOG or SOX2, this suggest that PI3K/AKT pathway does not regulate pluripotency genes in mesothelioma and that pluripotency factors act upstream of it." (PMID 32664372, 2020). "In mesothelium and mesothelioma, OCT4 protein was not expressed, but NANOG and SOX2 proteins were expressed in portion of cells." (PMID 32664372, 2020). "Conversely, it has been also shown that POU5F1, NANOG and SOX2 are not expressed in mesothelioma cell lines." (PMID 32664372, 2020).
metastatic malignant melanoma (1 paper, 2020). "Using the same iPSC markers, we have also shown the presence of two CSC subpopulations within head and neck metastatic malignant melanoma (HNmMM): an OCT4+/SOX2+/KLF4+/c-MYC+ CSC subpopulation within the TNs, and another in the PTS with NANOG present only in two of the 20 cases studied." (PMID 32850316, 2020).
metastatic prostate carcinoma (1 paper, 2023). A carcinoma that arises from the prostate gland and has spread to other anatomic sites. "NANOG may be suggested as a therapeutic target for metastatic prostate cancer." (PMID 37987305, 2023).
myxoma (1 paper, 2020). A benign soft tissue neoplasm characterized by the presence of spindle and stellate cells, lobulated growth pattern, and myxoid stroma formation. "Also, these clonogenic c-kitpos/CD45neg/CD31neg myxoma-derived CSCs express OCT-4, NANOG, BMI-1, NKX2.5, and ISL-1 and form cardiospheres at a rate similar to normal human CSCs even though serial spherogenesis was reduced." (PMID 32330934, 2020).
odontogenic cyst (1 paper, 2022). A cyst in the jaw that arises from tissues of tooth development. "Various stemness markers (SOX2, OCT4, and NANOG) have been studied in odontogenic cysts and tumors." (PMID 38895097, 2022).
odontogenic tumour (1 paper, 2023). "Immunohistochemical staining for SOX-2, NANOG and OCT4 was mainly located in the cords and islands of the odontogenic tumour epithelium." (PMID 36655039, 2023).
oropharyngeal squamous cell carcinoma (1 paper, 2017). "Two recent studies revealed the positive correlation between enhanced expression patterns of CD44v6 and NANOG in oropharyngeal squamous cell carcinoma (OSCC) patients." (PMID 29156833, 2017).
osteomyelitis (1 paper, 2020). An acute or chronic inflammation of the bone and its structures due to infection with pyogenic bacteria. "ERBB2, TWIST1, and NANOG were screened out as the most valuable osteomyelitis-related genes (OMRGs)." (PMID 32595631, 2020). "Results showed that TWIST1 and NANOG were significantly up-regulated in bone marrow cells, but not in peripheral blood cells, of S. aureus osteomyelitis mice." (PMID 32595631, 2020). "Therefore, up-regulation of TWIST1 and NANOG and down-regulation of ERBB2 might indicate activation of immune cells in response to S. aureus osteomyelitis." (PMID 32595631, 2020). "It is somewhat unexpected that the up-regulated expression of TWIST1 and NANOG was only found in the cells from bone marrow but not in those from blood and the expression of ERBB2 was only down-regulated in the cells from blood in implant-associated osteomyelitis mice models." (PMID 32595631, 2020).
ovarian small cell carcinoma (1 paper, 2007). A carcinoma that arises from the ovary and is characterized by the presence of small malignant cells. "We examined in situ expression of stem cell-related (NANOG, OCT-3/4, KIT, AP-2γ) and germ cell-specific proteins (MAGE-A4, NY-ESO-1, TSPY) using a tissue microarray consisting of 60 OGCT tissue samples and eight ovarian small cell carcinoma samples." (PMID 17274819, 2007).
parathyroid adenomas (1 paper, 2021). "Nuclear SOX2 expression was detectable in 18% of parathyroid adenomas (PAds, n = 34) involving 5–30% of cells, while OCT4 and NANOG were expressed at the nuclear level in a more consistent subset of PAds involving 15–40% of cells." (PMID 34199594, 2021).
periodontal diseases (1 paper, 2022). "While maintaining pluripotency through increased NANOG expression in non-inflammatory conditions to protect the cells from senescence, the inflammatory microenvironment and DAMPS in periodontal diseases can increasingly prime the TQ-endorsed TLR3." (PMID 35563755, 2022).
pharyngeal tumors (1 paper, 2020). "Strikingly, the impact of NANOG and SOX2 on outcome varied depending on tumor site and lymph node infiltration, specifically showing prognostic significance in pharyngeal tumors." (PMID 32635524, 2020). "According to our findings, NANOG protein expression is frequent in HNSCC, thereby emerging as an independent predictor of better prognosis in pharyngeal tumors." (PMID 32635524, 2020).
prostate (1 paper, 2014). "The reason for this was unknown; although, a strong correlation was identified between NANOG and HIF-1α expression, which may suggest that NANOG and HIF-1α co-operate in prostate carcinogenesis." (PMID 25120646, 2014).
rectal NET (1 paper, 2015). "In conclusion, DCLK1 may be a novel marker for rectal NET, potentially indicating the presence of the stemness gene product, NANOG." (PMID 26622789, 2015).
spontaneous abortion (1 paper, 2019). Expulsion of the product of FERTILIZATION before completing the term of GESTATION and without deliberate interference. "Likewise, preDSC lines expressed the multipotentiality markers OCT-4, NANOG, and ABCG2, their clonogenic efficiency ranged between 4 and 15%, they remained alive for weeks in xenogeneic transplants, and they had a therapeutic effect in an immune-based murine model of spontaneous abortion." (PMID 31200769, 2019).
testicular teratoma (1 paper, 2025). "In 129/SvJ Dnd1Ter/+ mice, acute foetal hypoxia (10% O2 for 12 h at E13.8–E14.3) increased bilateral testicular teratoma frequency from 3.3% to 64% and preserved OCT4/SOX2/NANOG expression as well as TGF-β family morphogen (Nodal) activity." (PMID 41582951, 2025).
urothelial carcinoma (1 paper, 2024). A malignant neoplasm derived from the transitional epithelium of the urinary tract (urinary bladder, ureter, urethra, or renal pelvis). "In urothelial carcinoma (UC) cells, ZNF671 re-expression inhibited tumor growth and invasion, in conjunction with downregulation of cancer stem cell markers (c-KIT, NANOG, OCT4)." (PMID 39595048, 2024).
Wilms tumor (1 paper, 2008). An embryonal neoplasm characterized by the presence of epithelial, mesenchymal, and blastema components. "Important for their relation to Wilm's Tumor, several of these TFs have previously been implicated in cancer (NANOG, GLI1, E2F1, POU5F1/OCT4, SPI-1, YY-1, GATA1, and C/EBP-β)." (PMID 18564415, 2008).
cancer (666 papers, 2008 to 2026). A tumor composed of atypical neoplastic, often pleomorphic cells that invade other tissues. "Mutations in SPOP that occur in cancer disrupt this regulatory mechanism, leading to the accumulation of NANOG and the promotion of cancer stem cell properties, ultimately contributing to prostate cancer progression." (PMID 40227962, 2025). "This, together with its effect on the expression of NANOG suggests a potential predisposition to cancer development, highlighting the potential oncogenic implications of Dido3 dysregulation." (PMID 40287726, 2025). "Pluripotency-associated factors such as OCT4 (POU5F1), SOX2, and NANOG are frequently implicated in dedifferentiation and cancer stem cell (CSC) maintenance, allowing tumor cells to regain developmental plasticity." (PMID 40722714, 2025). "Nucleotide sequence change in RAN (A > G; rs3803012) leads to modification of the binding site of the transcription factor NANOG, which is associated with the differentiation of pluripotent stem cells and various types of cancer." (PMID 36672288, 2023). "NANOG, a stemness-associated transcription factor, is highly expressed in many cancers and plays a critical role in regulating tumorigenicity." (PMID 37047234, 2023). "A less marked downregulation of NANOG expression after DOX treatment was also significantly linked to high grade cancer." (PMID 38124067, 2023). "NANOG, a master transcriptional regulator of stemness, is linked to cancer progression and chemoresistance." (PMID 36646707, 2023). "Another interesting emerged gene is NANOG, encoding for a transcription factor regulating the stemness, and likely involved in drug resistance of cancer cells." (PMID 37041632, 2023). "Cancer showing high NANOG expression is usually associated with high grade, advanced stage, worse overall survival, and resistance to treatment." (PMID 35186145, 2022). "Overexpression of NANOG in cancer is frequently associated with advanced stage, lymph node metastasis, poor differentiation, and resistance to treatment and has been shown to be strongly correlated with poor prognosis." (PMID 35008480, 2021). "This mutation also induced an increase in the cancer stem cell pool and the expression of NANOG, OCT4, and SOX2." (PMID 34066428, 2021). "NANOG has been implicated in the acquisition of cancer therapy resistance, and its overexpression in PC cells has been shown to reduce AR levels." (PMID 34948357, 2021). "A recent study reported that the clinical expression of the pluripotent factors OCT4, SOX2, and NANOG (OSN) in cancer patients was associated with treatment resistance of lethal cancers." (PMID 32493501, 2020). "NANOG is a transcription factor involved in the maintenance of stemness and often linked to cancer aggressiveness." (PMID 32503139, 2020). "Altogether these data unveil the great applicability potential of NANOG expression as an early cancer risk biomarker, commonly in epithelial premalignancies at different head and neck subsites." (PMID 31484317, 2019). "In this study, we confirm that clinical expression of pluripotent factors OCT4, SOX2 and NANOG is associated with treatment resistance and lethal cancers." (PMID 30742096, 2019). "On this basis, we investigated the role of NANOG protein expression as an early cancer risk biomarker in oral potentially malignant disorders (OPMD), and the impact on prognosis and disease outcomes in OSCC patients." (PMID 31484317, 2019). "Recently, the stem cell transcription factor NANOG has been described in clinical studies to be associated with appearance of cancer stem cells." (PMID 31268606, 2019). "Herein, we show that the NANOG-mediated repression of ICAM1 is a critical mechanism underlying the ability of cancer cells to escape natural killer (NK) cell attack during the initial stage of prostate cancer (PCa) formation." (PMID 31619256, 2019).
cancer (continued). "Our findings uncover a novel role for NANOG expression in laryngeal tumourigenesis, and its unprecedented application as biomarker for cancer risk assessment." (PMID 28894270, 2017). "Since immunohistochemical analysis of NANOG is relatively simple and easy to interpret, it seems reasonable to recommend this molecular test to be included as complementary marker for cancer risk assessment and decision-making." (PMID 28894270, 2017). "This work unveils the clinical utility of NANOG expression as cancer risk marker in patients with laryngeal dysplasias, showing superior predictive power to histology." (PMID 28894270, 2017). "This study investigates for the first time the role of NANOG expression in early stages of laryngeal tumourigenesis and its potential utility as cancer risk marker." (PMID 28894270, 2017). "Together our findings uncover a novel role for NANOG expression in laryngeal tumourigenesis, and its unprecedented clinical application as biomarker for cancer risk assessment in patients with precancerous lesions." (PMID 28894270, 2017). "The pluripotency transcription factor NANOG has been implicated in tumor development, and NANOG-expressing cancer cells manifest stem cell properties that sustain tumor homeostasis, mediate therapy resistance and fuel tumor progression." (PMID 27867534, 2016). "For example, functional assays have implicated NANOG as a key regulator of clonogenic growth, as well as tumorigenesis, therapy resistance and migration/metastasis in many cancers." (PMID 27867534, 2016). "In these other types of cancer higher NANOG and POU5F1 expression has been associated with greater resistance to chemotherapeutic agents and drug resistance has variously been attributed to mesenchymal-like characteristics and increased drug efflux." (PMID 24475288, 2014). "In conclusion, our results demonstrate that epigenetic regulation is important for the expression of pluripotency-associated genes in cancer cells, particularly NANOG, and contributes to the metastatic potential of CSCs." (PMID 24023739, 2013). "As CD133 has been considered to be a cancer stem cell marker in several tumor types, we examined mRNA expression of the stemness gene Oct-4, NANOG and metastasis-associated receptor CXCR4 using RT-PCR in the CD133+ population and its counterpart CD133− cells." (PMID 23181114, 2012). "Therefore, NANOG can act as an oncogene to promote carcinogenesis by inducing cancer stem cells and mitophagy-associated HCC progression." (PMID 38846985, 2024). "In this study, we noted that the cause of TRPV1 overexpression in cisplatin-resistant cancer was due to direct transcriptional regulation by NANOG, but other possibilities may exist." (PMID 37165076, 2023). "Conversely, the suppression of MALAT1 results in the downregulation of stem cell-associated genes OCT4 and NANOG, leading to the inhibition of cancer cell proliferation and migration and the formation of tumor spheres, while simultaneously promoting cell apoptosis." (PMID 38203269, 2023). "Also, the activation of core pluripotency transcription factor machinery, namely OCT4 (encoded by POU5F1), SOX2, Myc, or NANOG, is frequently observed in cancer stem cell-like tumor types and associated with worse patient survival." (PMID 36674511, 2023). "Additionally, the increased expression of NANOG is associated with higher tumor grades in different cancers, including HNSCC." (PMID 37626893, 2023). "In fact, elevated NANOG levels in cancer cells are known to be caused by hypoxia." (PMID 37461005, 2023). "An increased expression of NANOG is associated with poor survival in patients with cancer." (PMID 37047234, 2023). "NANOG is associated with an immune-refractory feature of the TME in patients with cancer." (PMID 35104240, 2022).